DIPK1A (divergent protein kinase domain 1A)
Synonyms: FAM69A; FLJ23493
Tractability: Antibody: UniProt predicts a signal peptide or a membrane-spanning region.
Gene: Protein-coding gene on chromosome 1 (92,832,737 to 92,961,522, reverse strand). Ensembl gene ENSG00000154511.
Subcellular location: Endoplasmic reticulum membrane
Subcellular location (Human Protein Atlas): Cytosol; Nucleoplasm
Gene Ontology:
Cellular component: endoplasmic reticulum membrane
Genetic constraint (gnomAD): Loss-of-function variants: 22 observed, 25.26 expected, observed/expected ratio (o/e) 0.87, 90% interval 0.62 to 1.24. The upper end of that interval is the gene's LOEUF score, 1.24, which puts it in group 5 of 6, group 1 being the genes least tolerant of losing a copy. Missense variants: 306 observed, 376.17 expected, observed/expected ratio (o/e) 0.81, 90% interval 0.74 to 0.89. Synonymous variants: 136 observed, 130.99 expected, observed/expected ratio (o/e) 1.04, 90% interval 0.9 to 1.2.
Homologues: Orthologues: chimpanzee DIPK1A (100% identical), macaque DIPK1A (99% identical), dog DIPK1A (99% identical), pig DIPK1A (99% identical), guinea pig DIPK1A (98% identical), mouse Dipk1a (97% identical), rat Dipk1a (96% identical), rabbit DIPK1A (94% identical), tropical clawed frog dipk1a (76% identical), zebrafish dipk1aa (66% identical), zebrafish dipk1ab (66% identical), Caenorhabditis elegans C53D5.1 (22% identical), and 1 more. Paralogues in human: DIPK1B (48% identical), DIPK1C (21% identical).
Diseases named in the same sentence as DIPK1A in open-access papers:
DIPK1A is named in the same sentence as 8 diseases in open-access papers, as found by Europe PMC text mining. Sharing a sentence is not in itself a finding about the gene and the disease.
DIPK1A shares sentences with these, for which no sentence is quoted: multiple sclerosis (2 papers); neurological diseases (2); schizophrenia (2); autism (1); bipolar disorder (1); colon cancer (1); epilepsy (1); myasthenia gravis (1).